TRPV2 (transient receptor potential cation channel subfamily V member 2)
Diseases named in the same sentence as TRPV2 in open-access papers (continued):
Sharing a sentence is not in itself a finding about the gene and the disease.
prostate carcinoma (continued). "TRPV2 has been implicated in numerous pathophysiological processes, including heart failure and various cancers, with early studies demonstrating that TRPV2 modulators binding to the S4/S5 linker or the VBP can suppress glioblastoma progression or reduce prostate cancer metastasis." (PMID 40773831, 2025). "Interestingly, it has been shown that TRPV2 expression and functionality in prostate cancer cells increases the expression of MMPs and CTSB." (PMID 34936030, 2021). "In bladder and prostate cancers, TRPV2 stimulates migration and invasion." (PMID 32751388, 2020). "All current evidence points to a role of TRPV2 in the process of prostate cancer (PCa) metastasis." (PMID 33376561, 2020). "It has been shown that urothelial carcinoma cells, human leukemic cells, prostate cancer cells, esophagus squamous cell carcinoma cells, and hepatocellular carcinoma cells overexpress TRPV2 channels." (PMID 31680972, 2019). "Similarly, TRPV2 mRNA expression was found to be ≈12 times higher in aggressive late stage metastatic human prostate cancer samples than in localized specimens, and TRPV2 silencing reduced prostate tumor development in a xenograft mouse model." (PMID 30733502, 2019). "Furthermore, TRPV2 was found to be enriched in several cancer types such as bladder and prostate cancer." (PMID 30235802, 2018). "In addition, the progression of prostate cancer to the castration-resistant phenotype is characterized by de novo TRPV2 expression, with higher TRPV2 transcript levels in patients with metastatic cancer." (PMID 24709905, 2014). "A role for TRPV2 in the invasive capability of prostate cancer cells has been recently reported." (PMID 24709905, 2014). "Indeed, recent studies from our laboratory have shown show that TRPV2 is expressed in the more aggressive prostate cancer cells and stimulates the migration and invasive phenotype of these cells." (PMID 23741410, 2013). "Taken together, these studies suggest that TRPV2 and TRPM8 (along with NKX3.1) may constitute a valuable immunohistochemical panel to diagnose prostate cancer, and may identify patients at risk of aggressive disease who need early therapeutic intervention (as opposed to watchful waiting)." (PMID 37240443, 2023). "Moreover, exogenous expression of TRPV2 increases migration in the prostate cancer cell line LNCaP." (PMID 31275168, 2019). "Indeed, the progression of prostate cancer to the castration-resistant phenotype is characterized by de novo expression of TRPV2, and higher levels of TRPV2 transcripts are found in patients with metastatic cancer (stage M1) as compared to primary solid tumors (stage T2a and T2b)." (PMID 24709905, 2014). "TRPV2 enhances migration process of prostate cancer cells through a TRPV2-mediated calcium influx, via Gq/Go, phosphatidylinositol-3,4 kinase (PI3,4K) signaling and translocation of TRPV2 from endosome to the plasma membrane." (PMID 32751388, 2020). "The activation of TRPV2 by lysophosphatidylcholine (LPC) and lysophosphatidylinositol (LPI) has been shown to induce calcium influx and increase cell migration in the prostate cancer cell line PC3, indicating the potential pathological role of TRPV2 in prostate cancer." (PMID 37569884, 2023). "Of MMPs, MMP2 and MMP9 were the main members presented to be regulated by SKA1 and TRPV2 in some cancers, such as human adenoid cystic carcinoma, non-small cell lung cancer and prostate cancer 20-22." (PMID 35813298, 2022). "The evaluation of TRPV2 as a key player in prostate cancer cell migration rather than cell growth was undertaken by in vitro as well in vivo studies." (PMID 33376561, 2020). "In addition, siRNA silencing of TRPV2 reduced the growth and invasion of PC-3 cells in xenograft models of prostate cancer and reduced the expression of invasive markers, MMP2, MMP9, and cathepsin-B, suggesting that inhibition of TRPV2 may reduce the aggressive phenotype of prostate cancer." (PMID 32825277, 2020).
prostate carcinoma (continued). "For instance, TRPV2, TRPV6, and TRPM8 were differentially expressed between normal prostate and prostate carcinomas." (PMID 27023518, 2016).
esophageal squamous cell carcinoma (23 papers, 2017 to 2025). Esophageal squamous cell carcinoma (ESCC) is a type of esophageal carcinoma (EC) that can affect any part of the esophagus, but is usually located in the upper or middle third. "Activation of TRPV2 or its overexpression was found to promote invasiveness of prostate cancer cells and is associated with advanced pathological stage in esophageal squamous cell carcinoma, respectively." (PMID 34671260, 2021). "TRPV2 overexpression was associated with high relapse-free survival in triple-negative breast cancer, whereas the opposite was found in patients with esophageal squamous cell carcinoma or gastric cancer." (PMID 33376561, 2020). "In glioblastoma multiforme, elevated TRPV2 expression correlated with increased patient survival while increased TRPV2 expression was associated with poor survival in esophageal squamous cell carcinoma." (PMID 29066974, 2017). "Among the biological processes regulated by TRPV2 channel during metastatic progression, TRPV2 has been notably associated with proliferation, for instance in esophageal squamous cell carcinoma, or with the progression toward a pro‐invasive phenotype in prostate and bladder cancers." (PMID 36744297, 2023). "Patients with esophageal squamous cell carcinoma harboring high expression levels of TRPV2 have a worse five-year overall survival rate after surgery when compared to patients with low TRPV2 expression." (PMID 36837670, 2023). "TRPV2 was over-expressed at both mRNA and protein levels in esophageal squamous cell carcinoma (ESCC) cell lines." (PMID 36033489, 2022). "For example, it has been reported that inhibition of TRPV2 expression reduces the proliferation and invasion of esophageal squamous cell carcinoma cells." (PMID 35406761, 2022). "Knockdown of ETV5 or its downstream genes SKA1 and TRPV2 significantly suppress Esophageal squamous cell carcinoma cells migration and invasion, respectively." (PMID 36052230, 2022). "Recently, pathway analysis conducted in esophageal squamous cell carcinoma revealed roles for TRPV2, WNT/β-catenin signaling and EMT." (PMID 34360952, 2021). "TRPV2 inhibition by tranilast was also cytotoxic and effectively decreased the number of tumor spheres in esophageal squamous cell carcinoma." (PMID 34671260, 2021). "In another comparative study, overexpression of TRPV2 in esophageal squamous cell carcinoma tissues, especially in the advanced stages of the disease, was found to correlate with poor prognosis of patients with this disease." (PMID 30733502, 2019). "High TRPV2 expression is also correlated with a poor prognosis of esophageal squamous cell carcinoma (ESCC)." (PMID 29772843, 2018). "Indeed, depletion of TRPV2 in esophageal squamous cell carcinoma cell lines resulted in decreased expression of WNT10A, TGFβ2, TGFβR2, GLI, Snai1, Zeb2, CDH2, CD44 and SOX2, and decreased the migratory potential." (PMID 34360952, 2021). "Indeed, pathway analysis revealed that TRPV2 regulates malignant potentials of esophageal squamous cell carcinoma cells via cross-talk between the hedgehog pathway and Wnt/β-catenin signaling." (PMID 34671260, 2021). "The link between abnormal TRPV2 expression and cancer progression has been widely studied and TRPV2 seems to exhibit oncogenic activity in cancers of the prostate and breast, as well as in esophageal squamous cell carcinoma, leukemia, multiple myeloma and glioblastomas." (PMID 34356643, 2021). "Patients with esophageal squamous cell carcinoma (ESCC) harboring high expression levels of TRPV2 had a worse five-year overall survival rate after surgery when compared to patients with low TRPV2 expression." (PMID 33376561, 2020). "Transient receptor potential vanilloid 2 (TRPV2) was previously shown to play an important role in the maintenance of cancer stem cells, and its specific inhibitor, tranilast, also has potential as a targeted therapeutic agent for esophageal squamous cell carcinoma (ESCC)." (PMID 33327342, 2020).
esophageal squamous cell carcinoma (continued). "Previously, it has been demonstrated that TRPV2 expression correlates with worse OS and PFS for triple negative breast cancer, esophageal squamous cell carcinoma, MM and gastric cancer." (PMID 32751388, 2020). "The inhibition of TRPV2 by tranilast; inhibition of ANO1 by T16Ainh-A01, digallic acid, and tannic acids; and the inhibition of voltage-gated sodium channels by valproic acid were reported as potential targeted therapeutic agents in esophageal squamous cell carcinoma." (PMID 37529379, 2023).
bladder cancer (22 papers, 2013 to 2025). "Upregulation of full-length glycosylated TRPV2 protein (f-TRPV2) in urinary bladder carcinoma is associated with metastatic ability, which can be regulated by short splice variant of TRPV2 (s-TRPV2)." (PMID 36045706, 2021). "In leukemia and bladder cancer, the oncogenic activity of TRPV2 was linked to alteration of its expression profile." (PMID 33376561, 2020). "The abundance of the s-TRPV2 variant in normal and low-grade bladder cancer tissues suggests that it may function as a regulator of f-TRPV2 isoform." (PMID 33376561, 2020). "Hence, the TRPV2 related pathophysiological situation in LBCs examined here is comparable to the clinical pathophysiological state caused by the differential expression of the two TRPV2 isoforms in bladder cancer." (PMID 30733502, 2019). "In the present study, the rat-TRPV2-encoding vector was transfected into 5637 cells, which are characterized by low levels of TRPV2 expression and relatively weak cell aggression, to verify the precise role of TRPV2 channels on bladder cancer." (PMID 24223658, 2013). "In fact, TRPV2 activation has been reported to induce apoptosis in an in vitro model of bladder cancer, and L-type calcium channel activity has been shown to trigger apoptosis through cytoplasmic calcium overload." (PMID 38042493, 2023). "TRPV2-mediated calcium influx can inhibit cell proliferation and induce apoptosis of bladder cancer cells." (PMID 35836291, 2022). "In our study, lysoPC promoted Ca2+ influx through TRPV2 and apoptosis in bladder cancer cells, which was similar to the effect of GPD1 overexpression." (PMID 35836291, 2022). "Downregulation of TRPM7 is known to play an important role in bladder cancer cell apoptosis 21,22 and TRPV2 is known to enhance bladder cancer cell migration and invasion but not cell proliferation." (PMID 35919815, 2022). "In bladder cancer, TRPV2 promotes tumor cell migration and invasion through metalloproteinase 2 (MMP2); in oesophagal squamous cell carcinoma, high expression of TRPV2 has confirmed to be related to the patient’s disease stage and overall survival." (PMID 34579758, 2021). "Nevertheless, the mechanism by which TRPV2 contributes to the pathogenesis of bladder cancer (BC) is not well understood." (PMID 33376561, 2020). "The oncogenic activity of the TRPV2 channel was first discovered in bladder carcinoma and was attributed to alteration of the channel transcription profile in urothelial carcinoma tissues and cell lines." (PMID 33376561, 2020). "As in bladder cancer, adrenomedullin induced TRPV2-dependent PCa cell metastasis to the bone by affecting the receptor activator of NF-κβ ligand (RANKL)." (PMID 33376561, 2020). "During the progression of bladder cancer from low (pTa, pT1, and pT2) to higher more aggressive (pT3 and pT4) grades, f-TRPV2 and s-TRPV2 expression levels increased and decreased, respectively." (PMID 33376561, 2020). "TRPV2 activation was also shown to promote bladder cancer cell metastasis via either matrix metalloproteinase-2- (MMP-2-) or adrenomedullin-dependent mechanisms in the human bladder carcinoma cell line T24/83." (PMID 33376561, 2020). "It has also been demonstrated that TRPV2 activation induces apoptotic cell death in human T24 bladder cancer cells." (PMID 24223658, 2013). "The aim of this study was to investigate the effects of TRPV2 on the proliferation, migration and invasiveness of 5637 bladder cancer cells, which are characterized by low TRPV2 expression." (PMID 24223658, 2013). "Rat TRPV2 cDNA was transfected into 5637 bladder cancer cells and changes in the behavior of the cells were detected." (PMID 24223658, 2013). "The aim of the present study was to investigate the effects of TRPV2 on the proliferation, migration and invasion of 5637 bladder cancer cells in vitro." (PMID 24223658, 2013). "The results of this study suggest that TRPV2 channels are a potential therapeutic target for bladder carcinoma." (PMID 24223658, 2013).
bladder cancer (continued). "Similarly, treatment of the mouse bladder carcinoma cell line MBT-2 with TRPV2 agonists 2-APB or LPC induced Ca2+ influx and inhibited cell proliferation, but TRPV2 silencing induced an opposite effect." (PMID 33376561, 2020). "In conclusion, TRPV2 negatively regulates bladder cancer cell proliferation and could be a potential therapeutic target for the treatment of bladder cancer." (PMID 33376561, 2020). "TRPV2 expression has been studied in prostate, bladder cancer and hepatocellular carcinoma." (PMID 30323891, 2018). "Furthermore, a recent study using 5637 bladder cancer cells transfected with rat TRPV2 cDNA, showed that TRPV2 overexpression enhanced bladder cancer cell migration and invasion by direct matrix metalloproteinase 2 (MMP2) regulation." (PMID 24709905, 2014). "Interestingly, TRPV2 expression in bladder is also shown to correlate with the grade and stage of cancer but nothing is known about its potential role in bladder cancer cell migration/invasion." (PMID 23741410, 2013). "It has been indicated that TRPV2 channels may be critical in the development and progression of bladder cancer, but their specific role remains unknown." (PMID 24223658, 2013). "The proangiogenic role we described here for TRPV2 adds another aspect to the tumorigenic properties of TRPV2, since this channel has been positively correlated with tumor progression to the castration-resistant phenotype in PCa and with tumor grade and stage in bladder cancer." (PMID 31288452, 2019). "However, the precise role of TRPV2 in bladder cancer in vivo requires further study." (PMID 24223658, 2013). "Furthermore, TRPV2 expression is also increased in higher bladder cancer stage." (PMID 23741410, 2013). "The knockdown of TRPV2 significantly inhibited the elevation of Ca2+ concentration and reduced apoptosis induced by G3P/NAD+ in bladder cancer cells." (PMID 35836291, 2022). "In this context, the expression of transient receptor potential vanilloid 2 (TRPV2), one of the key genes in the NOD-like receptor signaling pathway, was significantly increased in bladder cancer cells after GPD1 overexpression." (PMID 35836291, 2022). "Moreover, the s-TRPV2 variant was expressed in low-grade RT4 cells, and irrespective of grade of malignancy its expression progressively decreased in pTa, pT1, and pT2 and was undetectable in high grade EJ and J82 cells, and pT3 and pT4 invasive bladder cancer tissues." (PMID 24709905, 2014). "However, the precise role of TRPV2 in bladder cancer remains unclear." (PMID 24223658, 2013). "However, the role of TRPV2 in bladder cancer development and progression remains unclear." (PMID 24223658, 2013). "In bladder cancer cells, TRPV2 also enhanced cell migration and invasion but did not affect cell proliferation in vitro." (PMID 34356643, 2021). "In conclusion, the nonselective cationic TRPV2 channel enhances bladder cancer cell migration, but does not affect cell proliferation in vitro." (PMID 24223658, 2013). "It was observed that TRPV2 enhanced bladder cancer cell migration and invasion; however, it did not affect cell proliferation in vitro." (PMID 24223658, 2013).
glioblastoma (22 papers, 2014 to 2026). The most malignant astrocytic tumor (WHO grade IV). "One example is TRP vanilloid-2 (TRPV2), for which increased expression has been associated with temozolomide-resistant glioblastoma, tumor recurrence, and decreased patient survival." (PMID 36768856, 2023). "Loss or inactivation of TRPV2 promoted glioblastoma cell proliferation and increased resistance to CD95-induced apoptotic cell death." (PMID 33376561, 2020). "Analyses in 3 different cohorts have shown that the identified TRPV2 signature is able to discriminate between glioblastoma patients at low- and high-risk in terms of survival." (PMID 29719613, 2018). "The TRPV2 signature is also associated with glioblastoma patient age, disease progression, recurrence, and drug resistance." (PMID 29719613, 2018). "The TRPV2-interactome signature against available experimental data is capable of discriminating overall risk in glioblastoma multiforme prognosis, progression, recurrence, and chemotherapy resistance." (PMID 29719613, 2018). "Expression of the TRPV2 interactome was significantly associated with less survival of glioblastoma patients in a derivation and 2 validation cohorts." (PMID 29719613, 2018). "This new information could be used to guide therapeutic design to treat glioblastoma multiforme and other TRPV2 channel associated pathophysiological process." (PMID 31566564, 2019). "Consequently, loss or inactivation of TRPV2 signaling (e.g., glioblastomas), induces unchecked proliferation, resistance to apoptotic signals and increased resistance to CD95-induced apoptotic cell death." (PMID 24709905, 2014). "The drug probenecid, which targets TRPV2, has played a critical role in the treatment of glioblastoma and liver cancer." (PMID 40535121, 2025). "In glioblastoma, TRPV2 upregulates the expression of Fas/CD95 and Procaspase-8 mRNA, thereby inhibiting cell proliferation." (PMID 40535121, 2025). "Studies have demonstrated that TRPV2 is expressed in neural progenitor cells and glioblastoma stem cells (GSCs)." (PMID 40535121, 2025). "A similar observation was made in patients suffering from glioblastoma, where TRPV2 expression decreased with disease progression." (PMID 41118703, 2025). "Conversely, TRPV2 has been shown to inhibit glioblastoma cell proliferation and overcome their resistance to carmustine." (PMID 36768856, 2023). "In agreement with the previous observations, another study demonstrated that TRPV2 expression was downregulated in glioblastoma stem cells compared to differentiated cells." (PMID 36142596, 2022). "TRPV2 activation promotes differentiation and inhibits the proliferation of glioblastoma stem cells (GSCs) in vitro and in vivo." (PMID 34458247, 2021). "The eradication of some types of cancer (e.g., leukemia and bladder) requires induced loss or inhibition of TRPV2, whereas the suppression of other cancers (e.g., glioblastoma and breast) involves TRPV2 overexpression or activation." (PMID 33376561, 2020). "Another study in in vitro and in vivo models showed that TRPV2 enhances glioblastoma stem-like cells (GSCs) differentiation toward a more mature glial phenotype, and suppresses their proliferation." (PMID 30691160, 2019). "TRPV2 has been found to be expressed in both neural progenitor cells and glioblastoma stem/progenitor-like cells (GSCs)." (PMID 30845786, 2019). "Recent findings have demonstrated with RT-PCR and biochemical analyses the expression of the TRPV2 receptor in normal human astrocyte and glioblastoma tissues, with progressive reduction in TRPV2 expression as grade increases." (PMID 30845786, 2019). "In glioblastoma, TRPV2 inhibits survival and proliferation, and induces Fas/CD95-dependent apoptosis." (PMID 30845786, 2019). "Our study is in accordance to previous study that showed TRPV2 enhanced chemotherapeutic drug uptake in glioblastoma cell line." (PMID 30323891, 2018).